WDR43 (WD repeat domain 43)
Description:
Ribosome biogenesis factor that coordinates hyperactive transcription and ribogenesis. Part of the small subunit (SSU) processome, first precursor of the small eukaryotic ribosomal subunit. During the assembly of the SSU processome in the nucleolus, many ribosome biogenesis factors, an RNA chaperone and ribosomal proteins associate with the nascent pre-rRNA and work in concert to generate RNA folding, modifications, rearrangements and cleavage as well as targeted degradation of pre-ribosomal RNA by the RNA exosome. Involved in nucleolar processing of pre-18S ribosomal RNA. Required for optimal pre-ribosomal RNA transcription by RNA polymerase I. Essential for stem cell pluripotency and embryonic development. In the nucleoplasm, recruited by promoter-associated/nascent transcripts and transcription to active promoters where it facilitates releases of elongation factor P-TEFb and paused RNA polymerase II to allow transcription elongation and maintain high-level expression of its targets genes (By similarity).
Synonyms: KIAA0007; UTP5; NET12
Tractability: Small molecule: a structure with a bound ligand is known. PROTAC: UniProt records ubiquitination sites on it; ubiquitination databases record sites on it; its protein half-life has been measured.
Gene: Protein-coding gene on chromosome 2 (28,894,638 to 28,948,223, forward strand). Ensembl gene ENSG00000163811.
Subcellular location: Nucleus, nucleolus; Nucleus, nucleolus fibrillar center; Nucleus, nucleoplasm
Pathways (Reactome):
Metabolism of RNA: Major pathway of rRNA processing in the nucleolus and cytosol; rRNA modification in the nucleus and cytosol
Gene Ontology:
Molecular function: protein binding; RNA binding; RNA polymerase II complex binding; transcription elongation factor activity
Biological process: positive regulation of rRNA processing; positive regulation of transcription by RNA polymerase I; ribosomal small subunit biogenesis; maturation of SSU-rRNA; maturation of SSU-rRNA from tricistronic rRNA transcript (SSU-rRNA, 5.8S rRNA, LSU-rRNA); regulation of stem cell population maintenance; regulation of transcription elongation by RNA polymerase II; regulation of DNA-templated transcription
Cellular component: fibrillar center; nucleolus; small-subunit processome; chromatin; nucleoplasm; t-UTP complex
Genetic constraint (gnomAD): Loss-of-function variants: 11 observed, 75.75 expected, observed/expected ratio (o/e) 0.15, 90% interval 0.09 to 0.24. The upper end of that interval is the gene's LOEUF score, 0.24, which puts it in group 1 of 6, group 1 being the genes least tolerant of losing a copy. Missense variants: 742 observed, 743.25 expected, observed/expected ratio (o/e) 1, 90% interval 0.94 to 1.06. Synonymous variants: 312 observed, 267.36 expected, observed/expected ratio (o/e) 1.17, 90% interval 1.06 to 1.28.
Homologues: Orthologues: chimpanzee WDR43 (99% identical), macaque WDR43 (99% identical), dog WDR43 (93% identical), pig WDR43 (93% identical), rabbit WDR43 (90% identical), rat Wdr43 (87% identical), guinea pig WDR43 (87% identical), mouse Wdr43 (87% identical), tropical clawed frog wdr43 (60% identical), zebrafish wdr43 (54% identical). Paralogues in human: MAPKBP1 (13% identical), WDR62 (13% identical), TEP1 (12% identical), AHI1 (12% identical), POC1A (11% identical), WDR7 (11% identical), WDR27 (11% identical), WDR17 (11% identical), POC1B (10% identical), TBL2 (9% identical), WDR75 (9% identical), PAFAH1B1 (9% identical), and 14 more.